CTSZ (cathepsin Z)
Diseases named in the same sentence as CTSZ in open-access papers (continued):
Sharing a sentence is not in itself a finding about the gene and the disease.
cancer (25 papers, 2011 to 2025). A tumor composed of atypical neoplastic, often pleomorphic cells that invade other tissues. "Furthermore, Mendelian randomization analyses have indicated a genetic association between CTSZ and cancer risk, including PCa." (PMID 40568593, 2025). "CTSZ belongs to cathepsin family, which has been closely associated with cancer progression." (PMID 21966391, 2011). "Despite growing evidence of CTSZ involvement in various cancers, its expression pattern and clinical significance in PCa remain poorly defined." (PMID 40568593, 2025). "LFA cleavage alters cellular morphology and enhances motility, linking CTSZ to cancer progression and metastasis." (PMID 40568593, 2025). "Cathepsin Z is involved in cancer progression and inflammatory processes and has been shown to have protective effects in inflammatory gastric diseases." (PMID 39944834, 2025). "In order to validate the metabolic and immunosuppressive properties of Macro_APOE/CTSZ in cancer tissues, we used ST data from two CRC patients." (PMID 36587392, 2023). "The integrin-binding function of extracellular cathepsin Z has also been described in the context of cancer." (PMID 34864055, 2022). "Despite the widely available data regarding CTSZ mRNA levels in different types of primary malignant tumors, the information about CTSZ mRNA expression in the whole blood of cancer patients is limited." (PMID 34378678, 2021). "The intense expression of CTSZ mRNA in malignant tumor sites can be explained, at least in part, by the immune infiltration that often occurs in cancer tissues." (PMID 34378678, 2021). "Further macrophage-secreted cathepsin Z facilitates cancer cell invasion through RGD-dependent binding of integrin receptor." (PMID 35008858, 2021). "Furthermore, functional experiments demonstrated that silencing CTSZ markedly inhibited the proliferation, migration, and invasion of PCa cells, aligning with its pro-tumorigenic roles reported in other cancer types." (PMID 40568593, 2025). "In the current results, Macro_APOE/CTSZ is revealed to constitute the major source of cysteine cathepsin expression in cancer, which may be important for the functional differentiation and immunosuppressive properties of TAM." (PMID 36587392, 2023). "CTSZ is a lysosomal cysteine proteinase and is often expressed ubiquitously in cancer cell lines." (PMID 32101552, 2020). "Finally, our present study revealed that KMT2A epigenetically promotes cancer progression by targeting CTSZ, which has specific functions in cancer invasion and metastasis." (PMID 31090199, 2019). "The pro-metastatic role of CTSZ may serve as another clue to the development of cancer therapy, especially the inhibition of metastasis." (PMID 21966391, 2011). "We analyzed the proteome secreted by co-cultures of cancer cells and macrophages with variable genotypes of CTSB and the closely related CTSZ in vitro." (PMID 32385587, 2021). "The genes of CTSZ, AFF4, DHRS2, and HMGCS1 known as active agents in cancer progression, were identified as the central DEGs in the constructed PPI network in this study." (PMID 31528309, 2019). "To confirm the role of CTSZ in CRC, we further determined its expression levels in cancer and adjacent normal tissues." (PMID 31090199, 2019). "In this study, a cathepsin family member cathepsin Z (CTSZ), located in a frequently amplified region at 20q13.3, which is related to the enhancement of metastasis in various cancers, was identified to be upregulated in 43% of HCC samples." (PMID 21966391, 2011). "Since no data about the concentration of CTSZ mRNA in the total blood of cancer patients were available in the databases evaluated, we decided to explore this in a pilot clinical study based on blood samples of PCa patients." (PMID 34378678, 2021).
cancer (continued). "Using the Pan-Cancer TCGA dataset gathering RNA-seq data from 11,060 patients, an anticorrelation between TET2 expression and mRNA levels of lysosome proteins was confirmed for CLN3, CTSD, CTSF, CTSZ, IFI30, and NAGLU, suggesting TET2 might down-regulate lysosomal genes in various types of cancer." (PMID 35351824, 2022).
infection (9 papers, 2008 to 2025). The state of being infected such as from the introduction of a foreign agent such as serum, vaccine, antigenic substance or organism. "We are not the first to show a significant increase in CXCL1 levels following pathogenic infection in Ctsz−/− mice, but to the best of our knowledge, this is the first study to directly link CTSZ and CXCL1 during TB pathogenesis." (PMID 40924769, 2025). "Here, we show that CC strains harboring the Tip5S locus produce lower levels of CTSZ protein while exhibiting higher bacterial burden than B6 mice following aerosol infection, validating Tip5 as a susceptibility locus from the large-scale CC cohort screen." (PMID 40924769, 2025). "Leveraging published transcriptional data from genetically diverse mice, humans, macaques, and zebrafish, we find cathepsin Z expression is highest in macrophages following infection." (PMID 40924769, 2025). "We propose that CTSZ possibly acts on the mycobacterial membrane early in infection, killing a subset of the phagocytosed bacteria." (PMID 31117286, 2019). "The levels of CTSD seemed to be slightly increased in the U937 cells after infection with the 201 strain, and the levels of CTSZ showed no significant alterations during the infection." (PMID 31069175, 2019).
neurodegenerative disease (4 papers, 2024 to 2025). A disorder of the central nervous system characterized by gradual and progressive loss of neural tissue and neurologic function. "Cathepsin X (also called cathepsin Z), another cathepsin implicated in neuroinflammatory processes, is a key cysteine peptidase involved in degenerative processes during aging and neurodegenerative diseases." (PMID 41463031, 2025).
digestive system tumors (1 paper, 2024). "This analysis encompassed a total of nine cathepsins include cathepsin B, cathepsin E, cathepsin F, cathepsin G, cathepsin H, cathepsin L2, cathepsin O, cathepsin S, and cathepsin Z, and six digestive system tumors (HCC, PCa, BTC, CRC, GC, and EC)." (PMID 38590662, 2024).
infectious disease (1 paper, 2025). A disorder directly resulting from the presence and activity of a microbial, viral, or parasitic agent in humans. "A deeper understanding of how the functions of CTSZ impact disease severity could prove vital to developing therapeutic strategies for both endogenous and infectious diseases." (PMID 40924769, 2025).
CTSZ also shares sentences with these, for which no sentence is quoted: Alagille syndrome (2 papers); cutaneous melanoma (2); experimental autoimmune encephalomyelitis (2); Osteopenia (2); retinoblastoma (2); acute myeloid leukemia (1); adenocarcinoma (1); atherosclerosis (1); benign tumors (1); colon carcinoma (1); gastritis (1); glioblastoma multiforme (1); gouty arthritis (1); H. pylori (1); Huntington disease (1); latent infection (1); malignant ovarian tumors (1); myositis (1); pheochromocytoma (1); pulmonary arterial hypertension (1); pulmonary TB (1); renal cell carcinoma (1); renal dysfunction (1); rheumatoid arthritis (1); schistosomiasis (1); Sjogren syndrome (1); stress cardiomyopathy (1); Stroke (1); systemic lupus erythematosus (1); viral infection (1).